PDGFRB (platelet derived growth factor receptor beta)
Diseases named in the same sentence as PDGFRB in open-access papers (continued):
Sharing a sentence is not in itself a finding about the gene and the disease.
tumor (continued). "Additionally, clinical investigations revealed that PDGFRβ is not only strongly expressed in different tumor types but that the protein expression is important for disease prognosis." (PMID 22791264, 2013). "In addition, signaling of PDGFRβ has a key role in the regulation of tumor interstitial fluid pressure." (PMID 22791264, 2013). "However, PDGFRβ has been shown to be expressed in 50% of tumour cells in addition to 65% of peritumoural endothelial cells in GBM." (PMID 23638177, 2013). "To address this possibility, we initially investigated the pericyte coverage of blood vessels using two different methods, measurement of α-SMA staining (colocalized with VE-cadherin) of tumor sections and analysis of tumors for the pericyte marker PDGFRβ by Western blot." (PMID 23825230, 2013). "Consistent with several recent publications regarding the synergistic anti-tumor activity of rapamycin and sorafenib, our findings further demonstrate a novel mechanism that sorafenib enhances the anti-tumor effect of rapamycin through blockade of this PDGFRβ-dependent feedback loop." (PMID 22428038, 2012). "We next evaluated whether sorafenib could deconstruct PDGFRβ-dependent feedback loop and subsequently enhance the anti-tumor sensitivity of rapamycin." (PMID 22428038, 2012). "Strong expression of PDGFRβ was observed in the stroma of both tumor sets." (PMID 22630170, 2012). "We found that sorafenib could effectively inhibite phosphorylation of both AKT and ERK in a PDGFRβ-dependent manner, and subsequently enhance the anti-tumor sensitivity of rapamycin in vitro and in an immunocompetent orthotopic rat HCC model." (PMID 22428038, 2012). "Here, we demonstrate in a validated preclinical model a nearly complete tumor inhibition with a combination of two FDA-approved drugs (rapamycin and imatinib) targeting two distinct signaling pathways (mTORC1 and PDGFRβ, respectively) implicated in TS-associated neoplasia." (PMID 22765013, 2012). "Therefore, the use of a PDGFRβ tyrosine kinase inhibitor (TKI) should provide a novel strategy to interfere with pericyte function during tumour angiogenesis." (PMID 22304225, 2012). "Furthermore, Song and colleagues determined that reduction of PDGFRβ-expressing pericytes led to endothelial cell apoptosis, vascular dilation, and decreased tumor volume in pancreatic islet tumors in mice." (PMID 21385454, 2011). "Kaplan-Meier analysis showed that the watchful waiting patients with the highest quartile of PDGFRβ expression in tumor stroma had a significantly shorter cancer specific survival compared to the rest (15-year probability of event-free survival (P-EFS) was 67±5% and 34±9% in the two groups)." (PMID 20505768, 2010). "PDGFRβ expression in adjacent non-malignant tissue was also analyzed with regard to associations with tumor characteristics." (PMID 20505768, 2010). "However, a recent survey of patient archival biopsies showed that 93% of GBMs had detectable levels of PDGFRα and 37% had detectable PDGFRβ on tumor cells, while 93% and 100% had detectable levels in blood vessels, respectively." (PMID 19352490, 2009). "Therefore, the preliminary significance of PDGFRB in tumor detection can be inferred." (PMID 40128057, 2025). "In addition, a p.Pro925Ser mutation in PDGFRB, a receptor for PDGF correlated with alpha-fetoprotein, tumor size, and overall survival, was observed in the Oncopig HCC model 10 amino acids downstream (after accounting for homology) from a cBioPortal mutation that also formed a new Ser residue." (PMID 40340757, 2025). "It is possible that, as the tumor undergoes dedifferentiation, the solid growth increases and develops metastatic behavior; thus, cells lose receptors that are normally expressed by apocrine cells of the anal sac, even if the primary tumor and its metastasis continue to express PDGFRβ RNA." (PMID 41472102, 2025).
tumor (continued). "The inhibition of VEGFR and PDGFβ receptor (PDGFRβ) signaling to simultaneously target both endothelial cells and pericytes, respectively, has been investigated to enhance the efficacy of antiangiogenic tumor therapy and overcome the development of drug resistance in tumors." (PMID 39086395, 2024). "Therefore, the inhibition of PDGFRβ from an early stage of MASH may effectively suppress tumor development by alleviating these pathologies." (PMID 39394459, 2024). "Interestingly, PDGFRβ is known to promote tumor growth, metastasis, and resistance to therapy." (PMID 37294349, 2023). "However, others have shown differences in PDGFRβ expression in tumor settings." (PMID 36635273, 2023). "Besides, PDGFRB plays a pivotal role in angiogenesis and tumor cell proliferation." (PMID 36950012, 2023). "Furthermore, during exercise, endothelial cell recruitment is mediated by platelet derived growth factor receptor-beta (PDGFRβ) derived from platelets for tumor angiogenesis, dramatically reducing tumor hypoxia by upregulation of micro-vessel density and perfusion." (PMID 35246220, 2022). "This analysis showed that MMP14 expression was strongly correlated with that of genes related to stromal cells (including PDGFRB and VIM) as well as that of many collagen genes, suggesting that CAFs might contribute to tumor aggressiveness associated with MMP14." (PMID 36052235, 2022). "While studies have not examined the prognostic ramifications of tumor-cell PDGF/PDGFRβ expression, our results here using mouse and human tumors indicate a high likelihood that tumor cell PDGFRβ staining might provide prognostic information in BRCA1/INK4-RB-deficient tumors." (PMID 33478572, 2021). "Furthermore, additional mutations in PTCH1 (subclonal), PDGFRB, and the NAB2-STAT6 fusion were confirmed as a somatic event in tumor tissue, none of which have reported therapeutic options with clinical benefit in patient’s tumor type." (PMID 34452612, 2021). "The gene alterations that drive the development of PDGFRB wild‐type tumours remain unclear." (PMID 33830670, 2021). "However, it has not yet been shown if stromal cells provide the PDGFs or what impact stromal cells may have on tumor cells with high PDGFRβ." (PMID 33478572, 2021). "In addition, PDGFRb could simply be a marker for a functional fibroblast or vascular mural cell subset with distinct effects on tumor progression." (PMID 33661437, 2021). "However, in the multivariable analysis, high relative tumor PDGFRB area was not independently associated with overall survival." (PMID 33955203, 2021). "Interestingly, affibody-IR700 dye conjugate targeting PDGFRβ is predominantly distributed on pericytes inside tumors and induces tumor destruction via photodynamic therapy, with accompanying angiogenesis inhibition and tissue hypoxia, suggesting the possibility of removing pericytes using ADC." (PMID 35602228, 2021). "Interestingly, stromal SPARC expression correlated negatively with the MPM tumor cell marker staining (combination of CK5, calretinin, and CK5/6) (Spearman's rho: −0.432; p = 0.001) and positively with tumor cell PDGFRB expression (Spearman's rho: 0.314; p = 0.008)." (PMID 33955203, 2021). "Importantly, high expression of platelet‐derived growth factor receptor beta (PDGFRB) in tumor cells, but not in stromal cells, was associated with shorter survival (hazard ratio [HR] = 1.02, p < 0.001)." (PMID 33955203, 2021). "Additionally, repeated acquisition of PDGFRB copy number gains in tumours of different clades on the Freycinet Peninsula, coinciding with steady devil population decline, suggests the possibility of an arms race towards more virulent DFT1 forms driven by within-host inter-lineage competition." (PMID 33232318, 2020).
tumor (continued). "Additionally, all tumor models are syngeneic to C57BL/6 background, the same genetic background as the ASKA mutant mice; tumor cells were grown subcutaneously in the ASKA PDGFRβ mice, apart from EO771 that was orthotopically injected into the 4th mammary fat pad." (PMID 31938055, 2020). "Thus, for use of selective PDGFRβ future kinase inhibitors for treatment of epithelial tumors, stratification of patients based on tumor PDGF-BB expression may be necessary." (PMID 31938055, 2020). "However, PDGFRβ inhibition alone has shown little effect on tumor growth." (PMID 30777101, 2019). "Interestingly, our data are in line with Hosaka and colleagues showing that in the PMT occurring during the tumor growth and metastasis, the loss of PDGFRβ and NG2 is not due to pericytes death nor proliferation." (PMID 29875766, 2018). "Binding of this aptamer to the PDGFRβ was found to interfere with the receptor’s signaling cascade by preventing phosphorylation of the tyrosine kinase domains, thereby reducing cell proliferation and migration both in vitro and in athymic CD-1 nude mice tumour xenografts in vivo." (PMID 29189740, 2017). "Platelet-derived growth factor receptor β (PDGFRβ) is overexpressed on the pericytes of many types of tumors, suggesting that conjugation to PDGFRβ-binding molecules might deliver PS to tumor blood vessels." (PMID 29182023, 2017). "Although normal vessel density was noted under conditions of EC JAM-C deletion in the ID8 tumor vasculatures, EC JAM-C-deficient mice developed tumor blood vessels with significantly suppressed pericyte coverage, as indicated by reduced staining for α-SMA and PDGFRβ." (PMID 23825230, 2013). "Therefore, it is possible that claudin-low tumors present with elevated levels of PDGFRα and PDGFRβ, a characteristic that may improve the treatment of this class of tumor." (PMID 22070644, 2011). "Other genes in the area include PDGFRB, which plays an important role in tumor neovascularization, TGFBI, PTTG1, DOCK2 and DUSP1 (the latter three genes were speculated based on our internal studies), which were likely to be involved in ccRCC progression and development." (PMID 20671976, 2010). "Our functional experiments indicate that targeting PDGFRβ—thereby modulating stromal components of the TME, immune mediators, and tumor cell signaling—can substantially affect CRC cell growth and progression." (PMID 41601676, 2026). "Binding of DOTA-ATH022 in PDGFRβ avid and well-perfused spleen was 3 times higher than for DOTA-ATH001, but tumor binding was lower." (PMID 41840180, 2026). "We reveal PDGFRβ+ pericytes as key communication partners in the TME, contributing to stem cell signaling through extracellular matrix-mediated interactions with tumor cells." (PMID 40562749, 2025). "Identifying PDGFRA or PDGFRB rearrangements is critical, as imatinib effectively treats these conditions, whereas pemigatinib is approved for refractory FGFR1-rearranged neoplasms." (PMID 40508151, 2025). "We show that PDGFRβ+ PC from the TME interact with RG-like and NProg-like cells in vascular niches to support self-renewing tumor cells states." (PMID 40562749, 2025). "The “platelet-derived growth factor binding” and “insulin-like growth factor binding” signatures were among the top signatures enriched and the respective genes PDGFRβ, PDGFRα, and IGFL1 were among the top-enriched genes in mCAFhighendotheliahigh tumor niches." (PMID 41083996, 2025). "Targeting components of the tumor stroma (e.g., FAP, PDGFRβ), which exhibit lower antigenic variability, is also under investigation." (PMID 41262250, 2025). "All PDGCAs expressed markers of tumor epithelial and stem cells (EPCAM, CDH1, KRT18, CA9, CD24, CD133), stromal and extracellular matrix components (COL3A1, COL5A1, DCN, PDGFRA, and PDGFRB), and mesenchymal stem cells (CD73, CD105, CD90)." (PMID 40723172, 2025).
tumor (continued). "Aptamer Gint4.T, targeting the human platelet-derived growth factor receptor PDGFRβ ectodomain overexpressed in GBM, inhibits in vitro GBM cell migration and proliferation and decreased in vivo tumor growth and differentiation." (PMID 41012445, 2025). "The aim of this study was to investigate the expression of PDGFRα and PDGFRβ in RCC cells and assess their impact on tumor growth characteristics and patient prognosis." (PMID 40434293, 2025). "Within the tumor, SDF-1, SMA, and focal PDGFRB were observed in the thinner stroma strands and micro-vessels." (PMID 40841830, 2025). "Sorafenib, a multikinase inhibitor, exerts antineoplastic effects by inhibiting VEGF receptor (VEGFR), platelet‐derived growth factor receptor‐beta (PDGFR‐β), and Raf/MEK/ERK signaling cascades, thereby inhibiting tumor proliferation and angiogenesis." (PMID 40060195, 2025). "The progression of PCa is likely influenced by the interplay of these targets where FGFR1 drives tumor growth and metastasis, MMP-9 facilitates invasion, and PDGFRB promotes tumor growth and angiogenesis." (PMID 40429793, 2025). "SMA, PDGFRB, SDF1, POSTN, and DCN were also found in fibroblast-like cells within the connective tissue septa separating tumor cell nests, with POSTN and DCN occasionally present at the bone surface (data not shown)." (PMID 40841830, 2025). "Yet, the interaction between EphB4 and another RTK, namely platelet-derived growth factor receptor beta (PDGFRβ), in the presence of the PDGFRβ ligand, PDGF-BB, leads to tumor proliferation." (PMID 40508013, 2025). "In parallel, CDCP1-high tumor cells condition fibroblasts toward a myofibroblastic, pro-tumor phenotype (α-SMA, FAP, PDGFRβ, S100A4 upregulation), linking a tumor-intrinsic epigenetic program to stromal reprogramming." (PMID 41301830, 2025). "At the pathway level, signaling related to survival (PIP3/AKT), angiogenesis (VEGFR1/2, PDGFRB, and TXA2), and tumor-suppressive paracrine mechanisms (TRAIL) was enriched." (PMID 40564222, 2025). "In summary, short-term effects of ADT were observed on tumor cell nuclear AR levels and apoptosis, as well as on stromal POSTN and PDGFRB levels." (PMID 40841830, 2025). "The results showed that, compared to the control group, MIF knockdown in SCC7 cells resulted in a reduction in tumor size, accompanied by a significant decrease in the number of both CD74+PDGFRB+ and FAP+ cells." (PMID 39891284, 2025). "Subsequently, the PDGF-BB ligand activates PDGFRβ and EPHB4 through direct and indirect mechanisms, leading to the downregulation of Akt and Erk1/2 pathways, which enhance tumor cell survival and proliferation." (PMID 38233802, 2024). "PDGFRβ belongs to the type III receptor tyrosine kinase family and is known to be involved in tumor metastasis." (PMID 39273015, 2024). "This single cell transcriptomic analysis allowed us to identify the presence of macrophages (CD163), T cells (CD3D), and pericytes (PDGFRB), as well as endothelial (VWF) and folliculostellate (SOX2) cells, within the tumor microenvironment." (PMID 39217365, 2024). "Overall, 32.3% demonstrated high expression of PDGFRα, 17.7% for PDGFRβ, 19.8% for VEGFR2 and 8.3% exhibited positive expression for c-kit on the tumor cells." (PMID 39534097, 2024). "Regorafenib is an oral multi-targeted TKI, whose targets are involved in the regulation of tumor angiogenesis (VEGFR1–3 and TEK), oncogenesis (KIT, RET, RAF1, BRAF, and and BRAFV600E), and maintenance of the tumor microenvironment (PDGFRA, PDGFRB and FGFR)." (PMID 39165680, 2024). "Following digital analysis, we divided the patient cohort according to median expression in tumor stroma (FAP: n = 106 low, n = 105 high; PDGFRb: n = 106 low, n = 106 high; periostin: n = 106 low, n = 105 high; α-SMA: n = 107 low, n = 106 high)." (PMID 38328551, 2024).
tumor (continued). "PPARD agonists promote the expression of platelet-derived growth factor receptor beta, platelet-derived growth factor subunit B, and the tyrosinkinase KIT to promte tumor angiogenesis and progression." (PMID 38212774, 2024). "Next‐generation sequencing showed that most patients with tumor reduction expressed medium or high levels of VEGFR2 and PDGFRβ mRNA." (PMID 39618078, 2024). "PDGFRB was found to be significantly upregulated in aggressive TNBC tumor cells and the tumor microenvironment." (PMID 38329441, 2024). "Inhibition of PDGFRβ signaling significantly affects tumor progression and angiogenesis, depending on PDGF-BB expression, compromising pericyte coverage and tumor vascularization." (PMID 39086395, 2024). "PDGFRβ is frequently overexpressed in U87MG cells and plays a significant role in tumor progression, invasion, and treatment resistance in these tumors." (PMID 38675202, 2024). "Also, we proved that the Gint4.T aptamer, by binding to PDGFRβ expressed both on tumor cells and immune populations enhances the efficacy of anti-programmed cell death-ligand 1 monoclonal antibodies in inhibiting tumor growth and metastasis formation in a syngeneic TNBC mouse model." (PMID 38532439, 2024). "Descriptive data for tumor expression of c-Kit, VEGFR2, PDGFRα, PDGFRβ between different histological subtypes in the 96 pediatric patients with NRSTS." (PMID 39534097, 2024). "This study reveals for the first time a new mechanism by which ezetimibe acts on TNBC, that is, ezetimibe inhibits the growth of TNBC by inhibiting the activation of the PDGFRβ/AKT pathway, thereby inducing G1 blockade in tumor cells." (PMID 38027998, 2023). "IHC staining of both cell lines and the primary tumor tissue confirmed a stable expression of CCA tumor markers CK7, CK19, and e-cadherin, and the positive staining of stromal cells for vimentin and CAF markers α-SMA, TNC, and PDGFRB." (PMID 36980644, 2023). "KRT19 (tumor epithelial cells), PTPRC (CD45; immune/hematopoietic cells), and PDGFRB (stromal cells) were highly expressed by cells in different clusters." (PMID 37966117, 2023). "The combination of CAFs’ marker PDGFRB inhibitors and frontline PARP inhibitors substantially inhibited tumor growth and promoted the survival of OV-bearing mice." (PMID 37658364, 2023). "Interestingly, vCAFs shared many marker genes with pericytes, including platelet-derived growth factor receptor beta (PDGFRβ), Chondroitin Sulfate Proteoglycan 4 (CSPG4), and regulator of G protein signaling 5 (RGS5), which further supported its association with vascularization and tumor invasion." (PMID 38313431, 2023). "Cluster 8 ECs (COL1A1, COL1A2, COL3A1, PDGFRB, and ACTA2) showed an endothelium-mesenchymal transformation phenotype, contributing to tumor progression and metastasis." (PMID 37533434, 2023). "Immunohistochemical analysis of metastatic nodules in both lung and liver tissues from CRC and PDAC tumor‐bearing mice showed that metastases in Bmal1−/− mice were enriched in stromal fibroblasts that were positive for FAP, α‐SMA, DESMIN, PDGFRα, and PDGFRβ." (PMID 37330661, 2023). "Based on the mRNA expression profile of GC tumor and adjacent normal tissues from the GSE13861 and GSE54129 cohorts, FEN1, PDGFRB, SERPINE1, and TCF3 were up-regulated in tumor tissues, which coincide with their risk roles in the senescence-related signature." (PMID 37100457, 2023). "As previously observed in vitro, pladienolide B administration in vivo significantly decreased various relevant tumor progression markers and critical oncogenic spliceosome components (VEGFA/EGFR/CDK4/PDGFRA/PDGFRB and SRSF3/PTBP1)." (PMID 35086552, 2022). "The main question was the effect of denosumab treatment on mononuclear tumor cells (characterized by H3F3A immunopositivity), concerning PDGFRβ expression." (PMID 36091939, 2022).